GPNMB (glycoprotein nmb)
Diseases named in the same sentence as GPNMB in open-access papers (continued):
Sharing a sentence is not in itself a finding about the gene and the disease.
PEComas (1 paper, 2025). "tRCC and PEComas have highly overlapping epithelioid morphologies and immunophenotypes, including expression of melanocytic lineage genes and lysosomal markers (PMEL, MelanA, Cathepsin K, GPNMB) that are canonical MiT/TFE transcriptional targets." (PMID 41044182, 2025).
periodontitis (1 paper, 2022). An acute or chronic inflammatory process that affects the tissues that surround and support the teeth. "Glycoprotein nonmetastatic melanoma protein B (GPNMB) reduces LPS-induced apoptosis of PDLSCs as well as upregulates the expression of KDM6B, which could result in inhibiting the inflammatory response and apoptosis in periodontitis." (PMID 36187229, 2022).
peripheral nerve injury (1 paper, 2018). Injury to a peripheral nerve. "Based on our findings, GPNMB, ENPP3, Thbs2, and Lgals3 may play a key role in repair of SCs after peripheral nerve injury." (PMID 30186571, 2018).
pigmentary glaucoma (1 paper, 2023). Pigmentary glaucoma is a type of secondary open-angle glaucoma characterized by heavy homogenous pigmentation of the trabecular meshwork, iris transillumination defects, and pigment along the corneal endothelium (Krukenberg spindle). "In mice with pigmentary glaucoma, a premature stop codon mutation in the GPNMB gene results in iris pigment dispersal." (PMID 37627399, 2023).
protein misfolding diseases (1 paper, 2016). "The proteins encoded by APLP2, PTN, DCN, GPNMB, P4HB, and PDIA3, have been associated with either protein misfolding diseases or TSEs but their specific role in prion protein degradation has not been described." (PMID 26807844, 2016).
psoriatic arthritis (1 paper, 2024). Joint inflammation associated with psoriasis. "Additionally, in psoriatic arthritis, GPNMB is highly upregulated in synovial membranes and peripheral blood cells, suggesting its potential as a biomarker." (PMID 39263169, 2024).
rectal adenoma (1 paper, 2012). "Protein and mRNA expression of GPNMB was significantly higher in cancer tissues than rectal adenoma tissues." (PMID 23158542, 2012). "And the expression level of C13orf27 and GPNMB was significantly higher in cancer tissues than rectal adenoma tissues." (PMID 23158542, 2012). "Interestingly, both mRNA and protein expression of GPNMB was higher in cancer tissues than rectal adenoma tissues." (PMID 23158542, 2012). "The expression of GPNMB and DIS3 were further investigated in rectal adenoma and carcinoma tissues by immunohistochemistry." (PMID 23158542, 2012). "Array CGH found that copy number increase of GPNMB (7p15.2), OXGR1 (13q32.1), C13orf27 (13q32.2-q34), PMEPA1 (20q13.31), PHACTR3 (20q13.32) and decrease of SMAD4 (18q21.2), BCL2 (18q21.33) occurred in both rectal adenoma and carcinoma." (PMID 23158542, 2012).
rectal cancer (1 paper, 2012). A primary or metastatic malignant neoplasm that affects the rectum. "In twenty rectal cancer tissues, GPNMB and DIS3 were positively stained in six and five cases, respectively." (PMID 23158542, 2012). "In summary, we identified EFNA1 (1q), C13orf27 (13q), PMEPA1 (20q), GPNMB (7q) as candidate driving genes of genomic aberrations in rectal cancer." (PMID 23158542, 2012).
renal angiomyolipoma (1 paper, 2021). "Among the genes upregulated in the TSC2−/− organoids were: MLANA, PMEL, GPNMB, CTSK, and ACTA2, with median expression fold change 121x-, 88x-, 34x-, 14x-, 9.5x, respectively, all of which are known to be highly expressed in the renal angiomyolipoma." (PMID 34764250, 2021).
Renal cyst (1 paper, 2023). A fluid filled sac in the kidney. "GPNMB staining was significantly higher in renal cysts that were TFEB positive compared with normal human renal tubules." (PMID 36794754, 2023).
renal oncocytoma (1 paper, 2024). "Expression of biomarkers MAPRE3, ADGRF5, and GPNMB differentiates renal oncocytoma from chromophobe RCC, and PIGR and SOSTDC1 distinguish papillary RCC from MTSCC." (PMID 38703764, 2024).
sarcopenia (1 paper, 2025). Progressive decline in muscle mass due to aging which results in decreased functional capacity of muscles. "In other myopathies, ST identified Galectin-3–positive macrophages, GPNMB-expressing regenerative macrophages, and osteopontin/TGF-β signaling circuits as drivers of fibrosis or repair, offering translational insights into shared sarcopenia pathology." (PMID 40718353, 2025).
Skin rash (1 paper, 2018). A red eruption of the skin. "In the case of glembatumumab vedotin that targets the transmembrane glycoprotein NMB (gpNMB) on cancer cells, development of skin rash was one of the observed dose-limiting toxicities, which is likely due to membrane expression of gpNMB in epithelial cells of the skin." (PMID 29375935, 2018).
small cell lung carcinoma (1 paper, 2024). Small cell lung cancer (SCLC) is a highly aggressive malignant neoplasm, accounting for 10-15% of lung cancer cases, characterized byrapid growth, and early metastasis. "This study aimed to examine the correlation between plasma GPNMB levels and clinicopathological characteristics as well as prognosis in patients diagnosed with extensive stage small cell lung cancer (ES-SCLC)." (PMID 38706915, 2024).
subarachnoid hemorrhage (1 paper, 2023). A serious neurological disorder characterized by intracranial hemorrhage into the subarachnoid space. "GPNMB has been shown to have anti-inflammatory effects in a variety of neurological diseases, however, it has not been reported in subarachnoid hemorrhage (SAH)." (PMID 37919457, 2023).
systemic sclerosis (1 paper, 2022). A chronic disorder, possibly autoimmune, marked by excessive production of collagen which results in hardening and thickening of body tissues. "In this study, we set forth to determine the role of GPNMB in systemic sclerosis (SSc) fibroblasts." (PMID 35280996, 2022).
Takayasu arteritis (1 paper, 2022). A rare inflammatory large-vessel vasculitis primarily affecting the aorta and its major branches, but also other large vessels, causing stenosis, occlusion, or aneurysm. "They demonstrated that the risk allele A of rs2069837 in IL6 represses the expression of GPNMB by recruiting MEF2-HDAC complex, which is enabled through a long-range interchromatin looping in the Takayasu arteritis." (PMID 35368020, 2022).
uveal melanoma (1 paper, 2020). A melanoma derived from melanocytes of the uveal tract. "Glycoprotein NMB (GPNMB) is a transmembrane protein whose overexpression promotes the invasion and metastasis of cancer cells and is expressed at high levels in uveal melanoma." (PMID 32823698, 2020). "In preclinical studies, 86% of uveal melanoma specimens demonstrated positive immunohistochemistry (IHC) staining for GPNMB, though with variable intensity." (PMID 32823698, 2020).
tumor (142 papers, 2007 to 2026). "GPNMB is highly expressed in TECs and is associated with tumor growth and the exhaustion of tumor-infiltrating CD8+ T cells." (PMID 41180454, 2025). "Compared with control primary mouse BMDMs and microglia, GSC tumor-associated CD11b+CD45hiCD68+ macrophages and CD11b+CD45loCX3CR1+ microglia showed a higher GPNMB expression in both models." (PMID 40626360, 2025). "We applied 101 machine learning algorithms to evaluate the prognostic and immunological value of COL6A3+ tumor-associated fibroblasts (TAFs) and GPNMB+ monocyte-derived macrophages (MDMs) in multiple GBM cohorts and immunotherapy cohorts." (PMID 41174767, 2025). "CD44 is one of the functional receptors of GPNMB and is considered as a surface marker of cancer stem cells, interacting with tumor-associated macrophages." (PMID 41180454, 2025). "High expression of GPNMB is closely associated with various tumors, such as breast cancer, glioblastoma, and lung cancer, and promotes tumor growth, invasion, and metastasis." (PMID 40038549, 2025). "Glycoprotein NMB (gpNMB) is a glycoprotein expressed in various tumor cells and has been associated with promoting cancer progression." (PMID 39093344, 2024). "Loss of GPNMB in the in vivo tumor microenvironment results in significantly smaller tumor volumes and generates a pro-inflammatory innate and adaptive immune cell microenvironment." (PMID 38566120, 2024). "We demonstrate that GPNMB/OA expression enhances primary tumor growth, which is associated with diminished apoptosis and elevated recruitment of endothelial cells." (PMID 20711474, 2010). "GPNMB/OA expression promotes tumor growth, which is associated with enhanced endothelial recruitment." (PMID 20711474, 2010). "Within the tumor-associated myeloid cells, CD11b+CD45hiCD68+ macrophages and CD11b+CD45loCX3CR1+ microglia exhibited higher GPNMB expression compared with that of CD11b+CD45hiCD11c+ DCs, CD11b+CD68+Ly6GloLy6Chi monocytic IMCs, and CD11b+CD68+Ly6GhiLy6Clo polymorphonuclear IMCs." (PMID 40626360, 2025). "Accordingly, high gpNMB tumor expression levels are associated with poor clinical outcome." (PMID 35159045, 2022). "Preclinical studies have implicated gpNMB in tumor cell invasion, metastasis, and angiogenesis." (PMID 34016993, 2021). "Importantly, the GPNMB/OA-associated increase in tumor outgrowth observed in Balb/c mice was maintained even when cells were injected into immunodeficient mice, although to a lesser degree when compared to injections performed in Balb/c mice." (PMID 20711474, 2010). "Similarly, the UTR mutation chr7_23274960:A>T in GPNMB may also influence GPNMB expression, thereby promoting tumor metastasis." (PMID 40515555, 2025). "GPNMB can impact innate and adaptive immune function, decrease inflammation, promote tumor growth, and shield some cancers from immune/inflammatory defenses." (PMID 41462575, 2026). "All FLCN‐mutated tumours, including the sporadic ones and those with somatic FLCN mutations, appear to consistently and diffusely express GPNMB on IHC, which is reflective of the underlying mTORC1 dysregulation, leading to TFEB activation." (PMID 41384711, 2026). "GPNMB and FSTL1 have been linked to tumor invasion, metastasis, and modulation of the extracellular matrix." (PMID 40805206, 2025). "Against this backdrop of broader anti-tumor drug limitations, targeting GPNMB—despite its high expression in tumors—also presents notable challenges, with only its associated drug CDX-011 having entered clinical stages to date." (PMID 41180454, 2025). "GPNMB-positive cells exhibit a pro-metastatic phenotype and are enriched in metastatic sites, suggesting a potential role for quiescence in tumor dissemination." (PMID 40528051, 2025). "Disrupting GPNMB-mediated GSC-TAM interplay suppressed tumor progression and self-renewal in GBM mouse models." (PMID 40626360, 2025).
tumor (continued). "The results showed that the expression of GPNMB in both primary tumors and lymph node metastases was 100%, and the percentage of tumor cells expressing GPNMB was higher than that of EGFR." (PMID 41180454, 2025). "GPNMB-positive macrophages promote tumor cell proliferation and sphere-forming capability by transferring myelin-derived cholesterol and fatty acids to tumor cells through an LXR/Abca1-dependent pathway." (PMID 41180454, 2025). "GPNMB produced by macrophages plays a crucial role in proneural‒mesenchymal transition through immune cell‒tumor interplay, and GPNMB-high macrophages impair T cell activation by DCs." (PMID 40281508, 2025). "Together with the results in the current study, we propose that TAM-derived GPNMB serves as a key factor promoting tumor progression by regulating GBM cell metabolism." (PMID 40626360, 2025). "In mouse tumor models, M2 TAMs have been shown to preferentially express soluble GPNMB which combines with the CD44 receptor on tumor cells and promotes CSC proliferation via PI3K/AKT/mTOR or β-catenin/MAPKs/AMPK/Src signaling." (PMID 40380196, 2025). "In diffuse large B-cell lymphoma, silencing GPNMB can inhibit the nuclear translocation of β-catenin protein and weaken the malignant phenotype of tumor cells, which promotes tumor progression through the Wnt pathway." (PMID 41180454, 2025). "We used flow cytometry (FCM) sorting to isolate primary ICAM1+ MDMs and GPNMB+ MDMs from the tumor samples of GBM patients." (PMID 41174767, 2025). "GPNMB can promote tumor progression in different ways, such as enhanced cancer proliferation, survival, invasion, angiogenesis." (PMID 40528051, 2025). "In human GSC272 cells PDX model, we found that depletion of GPNMB in THP-1 macrophages or HMC3 microglia significantly prolonged the survival of tumor-bearing mice." (PMID 40626360, 2025). "Specifically, GSCs educated macrophages and microglia to preferentially express GPNMB in the GBM tumor microenvironment." (PMID 40626360, 2025). "In GBM, GPNMB has been shown to be highly expressed in TAMs, where it can promote tumor growth and impede T cell activation." (PMID 40626360, 2025). "Collectively, GPNMB exerts context-dependent roles across various tumors—while it drives tumor progression via mechanisms like immunosuppressive niche formation, metastatic promotion, and metabolic reprogramming in most cancer types." (PMID 41180454, 2025). "Collectively, these data demonstrate that while GPNMB+ cells promote invasiveness and drug-resistance, they contribute to a less proliferative state, leading to a paradoxical phenotype with delayed tumor formation." (PMID 40528051, 2025). "In SNV group 2, for example, chr22@328, chr7@232, and chr19@449 were associated with TIMP3, GPNMB, and APOE, respectively, which are marker genes of tumor-associated macrophages (TAMs)." (PMID 40515555, 2025). "While CCND1 and FOXI1 were enriched in the nuclei, GPNMB showed a homogeneous and moderate/strong expression within the cytoplasmic compartment of the chRCC tumor cells, and MAPRE3 protein showed a predominant membranous expression pattern in RO." (PMID 38703764, 2024). "This signalling pathway was of particular interest as GPNMB was highly enriched in basal tumour ROIs." (PMID 38890455, 2024). "In various types of cancer, the overexpression of GPNMB promoted the migration, invasion, and metastasis of tumor cells." (PMID 39263169, 2024). "Macrophages with high levels of GPNMB induce MET in tumor cells and inhibit T-cell activation, fostering an immunosuppressive microenvironment." (PMID 38720342, 2024). "The TCGA data set showed significantly higher expression of GPNMB in GBM compared to non-tumor tissue." (PMID 38566120, 2024). "GPNMB functions as a pro-tumorigenic factor predominantly by promoting tumor migration and invasiveness and elevating the levels of tumorigenic factors." (PMID 38924029, 2024).
tumor (continued). "In tumor-intrinsic knock-down and overexpression models, GPNMB has been described to promote cell growth, angiogenesis and invasion." (PMID 38566120, 2024). "Similar to its role in cancer and tumor growth, our results highlight GPNMB’s pattern of increased expression as shown in brain-related PD eQTLs." (PMID 38181731, 2024). "LUM+ tumor cells demonstrated a high expression of LUM, GPNMB, and CAVIN1 genes linked to low sensitivity to doxorubicin." (PMID 39685635, 2024). "In preclinical models, overexpression of gpNMB increases angiogenesis, inhibits tumor cell death, and encourages invasion and metastasis by a variety of tumor types." (PMID 39456611, 2024). "There is also evidence that a novel paracrine axis comprising GPNMB and IL-33 is activated by interactions between macrophages and tumor cells, ultimately promoting tumor cell survival, cancer stem cell expansion and metastasis development." (PMID 38351314, 2024). "Blocking GPNMB by antibodies restores the integrity of T cells, attenuates tumor growth, and increases interferon-gamma levels in the tumor microenvironment." (PMID 38822058, 2024). "At the invasive edge of the tumor, we observed higher levels of GPNMB, which were expressed by ameboid IBA1+ cells." (PMID 38566120, 2024). "Depletion of tumor endothelial cells (TECs) through the expression of glycoprotein nonmetastatic melanoma protein B (GPNMB) induces infiltration of CD8+ T cells into HCC tissue." (PMID 38426090, 2024). "Counting of GPNMB+/IBA1+ cells in each tissue specimen resulted in a mean percentage of 11.26% in non-tumor controls (Ctrl) and 66.06% in GBM slices (p = 0.0019)." (PMID 38566120, 2024). "GPNMB protein expression by IHC was high in the TFE3-fusion RCC tumor tissues that gave rise to the TFE3-fusion cell lines, but was largely negative in adjacent normal kidney parenchyma." (PMID 37095531, 2023). "The second aim is to explore the efficacy of the combination treatment with gpNMB-targeted antibody drug conjugate and dasatinib in shrinking the tumor." (PMID 36900378, 2023). "At present, the study of GPNMB is still in its infancy and the role of GPNMB in the multiple tumors or non-tumor cases requires to be further elucidated." (PMID 36820063, 2023). "Subgroups of mice were euthanized at 0-, 7-, 14-, and 21-days post treatment, and tumors were harvested for Western blot analysis of tumor cell lysates for gpNMB expression." (PMID 36900378, 2023). "There is growing evidence supporting that GPNMB is overexpressed among various cancers and it exhibits immunosuppressive function to promote tumor growth and metastasis." (PMID 38140790, 2023). "Deleting GPNMB in drug-resistant cells successfully restored tumour sensitivity to anti-PD-1 therapy." (PMID 36090016, 2022). "They firstly enrolled 42 patients with advanced/metastatic breast cancer, who were treated with standard 3 + 3 dose escalation followed by a phase II extension, and were confirmed by immunohistochemical gpNMB staining of tumor tissue." (PMID 36188535, 2022). "Previous studies reported that GPNMB production by macrophages promoted tumor progression and metastasis." (PMID 36470862, 2022). "Subsequent EMERGE clinical trial results showed that glembatumumab vedotin had a good and controlled safety feature, and that its activity was possibly intensified in patients with TNBC and/or gpNMB tumor expression." (PMID 36188535, 2022). "GPNMB has been shown to augment tumor growth and metastasis and to be overexpressed in cancers, enhancing tumor cell proliferation, migration, and invasion." (PMID 36361933, 2022). "GPNMB is a transmembrane glycoprotein that its role in cancer is complicated; It acts like a tumor suppressor or has a function in the cancer progression." (PMID 33724757, 2021). "Similar results were demonstrated in GPNMB-transduced tumor cells that showed a remarkably high tumorigenicity and metastatic ability in vivo." (PMID 34583655, 2021).